LATS1 (large tumor suppressor kinase 1)
Diseases named in the same sentence as LATS1 in open-access papers (continued):
Sharing a sentence is not in itself a finding about the gene and the disease.
breast cancer (continued). "Our data challenge this overly simplistic model, as LATS1/2 deletion inhibits ER+ breast cancer cell growth due to ESR1 transcriptional repression." (PMID 35217640, 2022). "Our analysis revealed a correlation between upregulated genes in LATS1/2-deleted cells and upregulated genes in Sox9hi cells when projected onto TCGA human breast cancers using single-sample GSEA." (PMID 36443313, 2022). "Altogether, these results indicated that Sox9+ luminal cells can serve as cells of origin for basal-like carcinomas driven by LATS1/2 deletion, reinforcing the implication of this lineage as an origin for basal-like breast cancers." (PMID 36443313, 2022). "Remarkably, overexpression of LATS1 in MDA-MB-468 cells was sufficient to render their gene expression pattern more similar to that of luminal breast cancer tumors (TCGA-BRCA dataset)." (PMID 36443319, 2022). "Furthermore, depletion of LATS1 from luminal MCF7 or ZR751 cells resulted in a global enrichment of ER-repressed gene expression, in line with the notion that restraining H3K27ac may be associated with LATS1-dependent maintenance of the luminal identity of human breast cancer cells." (PMID 36443319, 2022). "HERC4 is indicated to promote breast cancer progression via inhibiting tumor suppressor LATS1 via interaction with miRNA." (PMID 35064108, 2022). "In contrast, induced overexpression of LATS1 in human basal-like breast cancer MDA-MB-468 cells diminished H3K27ac levels." (PMID 36443319, 2022). "We also performed a similar analysis comparing Sox9 gene expression levels with the activity of genes upregulated by LATS1/2 deletion in human breast cancers, finding a strong correlation in the basal-like subtype." (PMID 36443313, 2022). "For example, EGFR, which is frequently mutated to a constitutively active form in lung and breast cancer, phosphorylates and represses MOB1, inactivating LATS1/2 and resulting in hyperactive YAP/TAZ." (PMID 35119068, 2022). "LATS1 is reported to regulate the transition of luminal-basal-like cell plasticity in breast cancer." (PMID 36443319, 2022). "We extended our analysis to the genes we identified as being upregulated and downregulated in LATS1/2-deleted mammary cells, which showed differing enrichment across human breast cancer subtypes." (PMID 36443313, 2022). "The upregulation of VGLL family genes by LATS1/2 deletion were further confirmed in ER+ breast cancer cell lines, as well as in ER+ tissue organoids, including mammary epithelial organoids, endometrial organoids and fallopian tube organoids." (PMID 35217640, 2022). "Ad-K8-nlsCre specifically targeted K8+ mammary luminal cells in a control tdTomato mouse and when injected into LATS1/2-floxed mice, 12 out of 19 mice developed overt mammary carcinomas over periods of 8–20 months after Cre delivery." (PMID 36443313, 2022). "Together, this demonstrates that PyMT mouse mammary carcinoma cells that retain LATS1 expression have an inherent preference to maintain a stable luminal cell state." (PMID 36443319, 2022). "Further, we found that gene expression signatures from basal-like breast carcinoma cells with high Sox9 levels correlate with those from LATS1/2-deleted luminal mammary epithelial cells." (PMID 36443313, 2022). "We demonstrated that deletion of LATS1/2 in mature mouse luminal cells leads to increased cell growth, luminal-basal plasticity, and initiation of basal-like mammary carcinomas dependent on the activity of the transcriptional regulators YAP and TAZ." (PMID 36443313, 2022). "Taken together, the results of this study indicate that PLE suppressed cell growth and increased the apoptosis of breast cancer (BC) cells via inactivation of YAP activity in a LATS1/2-dependent manner." (PMID 33628300, 2021). "RASSF1A and the Hippo-kinases LATS1/2 are of particular importance for the suppression of ERα-driven breast cancer." (PMID 34831091, 2021).
breast cancer (continued). "The main Hippo components are differentially expressed across cancer types, such as in the cases of MST1/2 in soft tissue sarcomas, LATS1/2 in astrocytoma and breast cancers, TAZ in breast cancer, and MOB1 in lung and colon cancers." (PMID 32722184, 2020). "It has been shown that LATS is a tumor suppressor in human cancer cells, and reduced expression of LATS1 or LATS2 can promote aggressive phenotype in human breast cancers." (PMID 33247672, 2020). "Here we demonstrate that HERC4 promotes breast cancer progression by destabilizing tumor suppressor LATS1." (PMID 30710319, 2019). "Our discovery of the functional link between miRNAs, HERC4 and LATS1 reveals a pathway that plays important roles in human breast tumorigenesis and provides new therapeutic targets for breast cancer treatment." (PMID 30710319, 2019). "However, the association of ER and Lats1 with breast cancer metastasis remains unclear." (PMID 31419991, 2019). "The overexpression of LATS1 reversed the tumorigenic activities induced by the overexpression of HERC4 in breast cancer cells." (PMID 30710319, 2019). "Our findings indicate that CRABP2 can suppress invasion and metastasis of ER+ breast cancer and promote invasion and metastasis of ER− breast cancer by regulating the stability of Lats1 in vitro and in vivo, and it provides new ideas for breast cancer therapy." (PMID 31419991, 2019). "Meanwhile, CRABP2 promotes the degradation of Lats1 by promoting ubiquitination of Lats1 in ER− mammary cancer cells." (PMID 31419991, 2019). "LATS1 is a potent tumor suppressor, and the inactivation or degradation of LATS1 promotes the development of various human cancers, including breast cancer." (PMID 30710319, 2019). "The interaction of endogenous and exogenous CRABP2 with Lats1 can regulate Lats1 by regulating ubiquitination of Lats1 in ER+ and ER− mammary cancer cells respectively." (PMID 31419991, 2019). "In conclusion, these data indicate that the regulation of CRABP2 on the EMT, metastasis, and invasion depends on Lats1 in ER− mammary cancer cells." (PMID 31419991, 2019). "The results showed that overexpression of CRABP2 increased the expression of Lats1 when ER was knocked down in ER+ breast cancer cells." (PMID 31419991, 2019). "The data presented in this study suggests that CRABP2 stabilize Lats1 by inhibiting ubiquitination of Lats1 in ER+ mammary cancer cells." (PMID 31419991, 2019). "d-f The regulation of CRABP2 on the metastasis, and invasion depends on Lats1 in ER- mammary cancer cells." (PMID 31419991, 2019). "In general, our study has identified the role of CRABP2 in breast cancer invasion and metastasis, which further depends on Hippo-Lats1 and ER status." (PMID 31419991, 2019). "We discovered that HERC4 is a new E3 ligase of LATS1 and can destabilize LATS1 in both normal breast epithelial cells and breast cancer cells by inducing the ubiquitination of LATS1." (PMID 30710319, 2019). "Large tumor suppressor 1 (Lats1) is a core component of the Hippo pathway and is vastly related to low lymph node metastasis of breast cancers." (PMID 31419991, 2019). "d-f The regulation of CRABP2 on metastasis, and invasion depends on Lats1 in ER+ mammary cancer cells." (PMID 31419991, 2019). "Using co-immunoprecipitation (CO-IP) assay, we confirmed the interaction between HERC4 and LATS1 in breast cancer cells." (PMID 30710319, 2019). "In ER+ mammary cancer cells, the interaction of CRABP2 and Lats1 suppress the ubiquitination of Lats1 to activate Hippo pathway to inhibit the invasion and metastasis of ER+ mammary cancer." (PMID 31419991, 2019). "Jointly, these data show that the regulation of CRABP2 on the EMT, metastasis, and invasion depends on Lats1 in ER+ mammary cancer cells." (PMID 31419991, 2019). "RT-qPCR technique was used to examine the particular relation between CRABP2 and Lats1 in mammary cancer cells." (PMID 31419991, 2019).
breast cancer (continued). "But, overexpression of CRABP2 in ER− mammary cancer cells reduced the protein levels of p-Lats1T1079, Lats1, p-YAPS127 and retained the protein expression of YAP and Mst2." (PMID 31419991, 2019). "From the previous study, it is known that knockdown of CRABP2 in ER+ mammary cancer cells and overexpression of CRABP2 in ER− mammary cancer cells promote the degradation of Lats1." (PMID 31419991, 2019). "To further examine this possibility, we generated a LATS1L 20-gene signature, comprising genes that were selectively down-regulated in LATS1-low human breast tumors and evaluated its expression in different breast cancer subtypes." (PMID 30456386, 2018). "We observed that deletion of Lats1 in a lumB-prone breast cancer model results in tumors that exhibit histology and gene expression patterns partially resembling ER-negative, basal-like tumors." (PMID 30456386, 2018). "In breast cancer, a recent work revealed that while LATS1/2 and MST1/2 reduce the expression of the immune checkpoint molecule PD-L1 in cancer cells, YAP/TAZ have an opposite effect." (PMID 30619734, 2018). "Silencing of LATS1 in MCF7 cells resulted in increased expression of genes associated with resistance to hormone therapy, particularly tamoxifen, supporting a role for LATS1 in maintaining estrogen dependence of luminal breast cancer cells." (PMID 30456386, 2018). "To gain insight into the impact of LATS1 and LATS2 deregulation on breast cancer, we examined the correlation between the expression levels of LATS1 and LATS2 in human breast cancer samples (TCGA- BRCA dataset)." (PMID 30456386, 2018). "Congruous with the changes in ER and CK14 levels in Lats1-CKO PyMT tumors, the expression pattern of Lats1-CKO PyMT tumors was similar to other ER-negative mouse mammary tumors and dissimilar to mature luminal cells." (PMID 30456386, 2018). "Knockout of Lats1 and Lats2 increases proliferation of biliary epithelium and hepatoblasts, in contrast, overexpression of Lats1 reduces proliferation of human breast cancer cells MCF-7." (PMID 28257933, 2017). "In good accordance, the treatment of breast cancer cells with MG132 proteasome inhibitor induced LATS1 increase." (PMID 27759563, 2016). "A previous study has shown that LATS1 kinase degradation occurs through polyubiquitination and the proteasome pathway in breast cancer cells." (PMID 27759563, 2016). "The E3 ubiquitin ligase ITCH has been previously reported to inhibit the tumor suppressive Hippo signaling by suppressing LATS1/2 in breast cancer and chronic lymphocytic leukemia." (PMID 26621835, 2016). "Aberrant expression or gene mutation of LATS1 contributes to malignant transformation and histological progression in cervical squamous cell carcinoma (CSCC), breast cancer, hepatocellular carcinoma (HCC) and astrocytoma." (PMID 26921249, 2016). "Some tumors such as breast cancer and astrocytoma have shown downregulation of LATS1 and LATS2 mRNA expression through promoter methylation." (PMID 26942001, 2016). "Data gathered so far indicate that MG decreases LATS1 expression in breast cancer cells, through the proteasome, which leads to sustained activity of YAP in the nucleus." (PMID 27759563, 2016). "Down-regulation of LATS1 expression due to its promoter hyper-methylation was also observed in breast cancer, colorectal cancer and astrocytoma." (PMID 25628642, 2014). "Negative regulation of LATS1 function was shown to mediate WWP1-induced breast cancer cell proliferation." (PMID 25350971, 2014). "LATS1 expression is significantly decreased in some tumors including breast cancer and astrocytoma, and this downregulation has been attributed to its promoter hypermethylation." (PMID 22909338, 2012). "Hypermethylation of the LATS1 gene promoter and reduction in mRNA expression was documented in some human breast cancers, soft tissue sarcomas and astrocytomas." (PMID 19656388, 2009).
breast cancer (continued). "In both cases, cervical cancers and basal-like breast cancers, LATS1 expression was higher in the tumor than in the normal tissue." (PMID 19656388, 2009). "Similarly, a recent study demonstrated that intraductal injection of Ad-K8-Cre to mammary ducts of Lats1/2-floxed female mice resulted in the development of mammary tumors displaying luminal-basal plasticity and features of epithelial-mesenchymal transition." (PMID 40622584, 2025). "Similarly, in breast cancer, the level of m6A modification of the tumor suppressor LATS1 mRNA is upregulated, resulting in the downregulation of LATS1 expression and promoting cancer development and progression." (PMID 38576024, 2024). "Thus, the expression of LATS1 and the phosphorylation of proteins in the Hippo pathway in breast cancer were inhibited, ultimately leading to glycolysis and tumor development." (PMID 36609396, 2023). "Moreover, the seahorse assay revealed that glycolysis was upregulated when LATS1 expression was suppressed after METTL3 expression was deleted in breast cancer cells." (PMID 36609396, 2023). "However, the protein level of LATS1 was inversely correlated with the expression of YTHDF2 in breast cancer cells." (PMID 36609396, 2023). "Furthermore, we investigated the phosphorylation levels and localization of YAP/TAZ to reveal that the activity of the Hippo pathway was affected by m6A regulation of LATS1 in breast cancer cells." (PMID 36609396, 2023). "In addition, the protein levels of METTL3 were inversely correlated with the mRNA levels of LATS1 in breast cancer cells." (PMID 36609396, 2023). "This apparent mutual exclusivity between NCOR1 mutations and LATS1 downregulation suggests that NCOR1 inactivation and decreased LATS1 expression may have a redundant impact on breast cancer, in agreement with their proposed shared mechanism of action." (PMID 36443319, 2022). "Loss of LATS1/2 selectively suppresses the proliferation of ERα+, but not ERα−, breast cancer cells." (PMID 36294681, 2022). "In estrogen receptor-alpha positive (ERα+) breast cancer, LATS1/2 regulates ERα expression." (PMID 36294681, 2022). "However, this study also reports that inhibition of LATS1/2 represses luminal breast cancer cell growth and tumorigenesis, which contrasts with the strong tumorigenic induction we observed in vivo following LATS1/2 deletion." (PMID 36443313, 2022). "In the mammary glands of LATS1 knockout transgenic mice, it was found that the mammary epithelial tissue was absent and showed an undeveloped state, demonstrating that it is necessary for breast cancer development." (PMID 36009693, 2022). "HERC4 interacts with miRNA and induces breast cancer progression via inhibiting LATS1." (PMID 35064108, 2022). "We now report that the tumor suppressor LATS1, whose expression is often downregulated in human breast cancer, helps maintain luminal breast cancer cell identity by reducing the chromatin accessibility of genes that are characteristic of a “basal-like” state, preventing their spurious activation." (PMID 36443319, 2022). "Furthermore, the loss of heterozygosity of LATS1 and frequent copy number loss of LATS2 are often observed in breast cancer." (PMID 34831091, 2021). "Moreover, WWP1 promoted LATS1 ubiquitination and degradation, leading to promoting proliferation of breast cancer cells." (PMID 34226507, 2021). "In addition, activation of the Hippo pathway by reconstituting NF2 expression in NF2-null breast cancer cell lines results in a robust LATS1/2-dependent inhibition of YAP/TAZ activity." (PMID 32960816, 2020). "CRABP2 ′s role in breast cancer may be related to oestrogen signalling that suppresses the ubiquitination of Lats1 to activate the Hippo pathway, which inhibits invasion and metastasis in ER-positive tumours but not in ER-negative tumours." (PMID 32927694, 2020). "We guessed what the mechanism might be that ER is more capable of binding to E3 ubiquitin ligase of Lats1 than CRABP2 in ER+ breast cancer cells." (PMID 31419991, 2019).
breast cancer (continued). "Thus, from these results, we conclude that that CRABP2 mediates ubiquitination of Lats1 in mammary cancer cells relying on ER status." (PMID 31419991, 2019). "Also, CRABP2 cannot bind to E3 ubiquitin ligase to suppress ubiquitination of Lats1 to repress invasion and metastasis of ER+ breast cancer." (PMID 31419991, 2019). "Likewise, knockdown of CRABP2 increased the expression of Lats1 when ER was overexpressed in ER− breast cancer cells." (PMID 31419991, 2019). "In addition, the protein levels of HERC4 were inversely correlated with the protein levels of LATS1 in breast cancer cells, supporting the notion that HERC4 negatively regulates the protein levels of LATS1." (PMID 30710319, 2019). "Next, we wished to examine the impact of Lats1 on breast cancer development in PyMT mice." (PMID 30456386, 2018). "This is consistent with canonical YAP/TAZ inhibition by LATS1 in the human breast cancer setting." (PMID 30456386, 2018). "We then asked whether STARD13-correlated ceRNA network modulates breast cancer cells stemness through LATS1/2." (PMID 29848346, 2018). "We examined the consequences of down-regulation of either LATS1 or LATS2 in breast cancer." (PMID 30456386, 2018). "Furthermore, both MG and 17-AAG decreased LATS1 expression in the three breast cancer cell lines under study." (PMID 27759563, 2016). "LATS1 is down-regulated in various human cancers, such as breast cancer, and astrocytoma." (PMID 25628642, 2014). "Importantly, we also showed that degradation of LATS1 is critical in mediating WWP1-induced increased cell proliferation in breast cancer cells." (PMID 23573293, 2013). "We have also shown that WWP1 regulates breast cancer cell proliferation by down-regulating LATS1." (PMID 23573293, 2013). "In addition, although LATS1 has been found down-regulated in breast cancer, how LATS1 interacts with other proteins in mammary tumorigenesis remains elusive." (PMID 23573293, 2013). "Since WWP1 is an oncogene and LATS1 is a tumor suppressor gene in breast cancer, our studies provide a promising therapeutic strategy in which developed drugs targeting WWP1 cause activation of LATS1 in suppressing breast cancer cell growth." (PMID 23573293, 2013). "Interestingly, two other studies documented the overexpression of LATS1 in human cervical cancers and basal-like breast cancers." (PMID 19656388, 2009). "Another lncRNA associated with breast cancer is the small nucleolar RNA host gene 9 (SNHG9), which correlates with breast cancer progression and other types of cancer and was found to interact with PA (phosphatidic acid) and Large Tumor Suppressor Kinase 1 (LATS1)." (PMID 40801625, 2025). "The results suggest that PLE inhibits cell growth and increases apoptosis in breast cancer (BC) cells by inactivating YAP activity in a LATS1/2-dependent manner." (PMID 37570851, 2023). "Together, this supports the conjecture that in both PyMT mouse mammary carcinoma cells and human breast cancer cell lines, LATS1 may maintain luminal identity by facilitating the repression of a subset of genes, including ERα-repressed genes, which should remain silent in luminal cells." (PMID 36443319, 2022). "Notably, we also found that human breast tumors with high activity of genes upregulated with LATS1/2 deletion in our model showed poorer survival over time, supporting the premise that LATS1/2 function as suppressors of aggressive traits in human breast cancers." (PMID 36443313, 2022). "Therefore, inhibition of WWP1 could be a promising approach for activation of LATS1 and further blocking growth of breast cancer cells." (PMID 34226507, 2021). "Therefore, HERC4-mediated degradation of LATS1 could represent a major oncogenic pathway in breast cancer." (PMID 30710319, 2019). "In addition, CRABP2 intervenes ubiquitination of Lats1 in breast cancer cells based on ER status." (PMID 31419991, 2019).